ADAM17 (ADAM metallopeptidase domain 17)
Diseases named in the same sentence as ADAM17 in open-access papers (continued):
Sharing a sentence is not in itself a finding about the gene and the disease.
tumor (continued). "Therefore, we shed light on the effect of RA on ADAM17 expression and found that RA considerably inhibited the expression of ADAM17 together with the downstream mediators of ADAM17, which constitutes ADAM17/EGFR/AKT/GSK3β axis and represents a crucial pathway for tumor progression." (PMID 34224305, 2021). "The inhibition of ADAM17 (GW280264X) in combination with cisplatin results in the synergistic inhibition of viability, and synergistic enhancement of apoptosis even occurs in primary tumor- and ascites-derived OvCa spheroids, thus being a promising target for future combinatorial treatments." (PMID 33922533, 2021). "Expression of ADAM17 showed a trend toward inverse correlation with PD-L1 within both tumor regions and cell types, but without statistically significant differences (TC-MIBC: rs = −0.413, p = 0.170; TC-CIS: rs = −0.198, p = 0.486; IC-MIBC: rs = −0.348, p = 0.215; IC-CIS: rs = −0.365, p = 0.184)." (PMID 33672843, 2021). "Furthermore, reports also demonstrate cytoplasmic localization of ADAM17 (not targetable by MEDI3622) in different tumor entities, but its cytoplasmic role has not been further investigated." (PMID 36860547, 2021). "In the murine APCmin/+ model of colon cancer, it was established that the genetic deletion of ADAM17, which is responsible for generating not only sIL-6R but also soluble TNFα and soluble ligands of the epidermal growth factor receptor (EGFR), resulted in completely abrogated tumour development." (PMID 32864098, 2020). "Interestingly, none of the mice injected with ADAM17 LEE cells reached tumor endpoint criteria, as opposed to ADAM17 wt or I762A injected mice, which exhibited only 50% survival by the end of the experiment." (PMID 32400009, 2020). "However, neither Cluxton nor our group detected enhanced ADAM10 (or ADAM17) transcription in tumor cells upon exposure to platelets (or platelet releasate)." (PMID 32117229, 2020). "Interestingly, ADAM10 and ADAM17 are not upregulated in the tumour cell, suggesting a novel and distinct process to regulate NKG2DL cleavage on the tumour cell surface." (PMID 30908480, 2019). "Thus, pharmacological modulation of iRHOM2 by targeting two stress-response proteins, K16 and ADAM17, could provide a specific therapeutic strategy in the treatment of PPK's, inflammatory epithelial disease and neoplasia." (PMID 28128203, 2017). "Cleavage of TβR1 by ADAM17/TACE and Presenilin 1, a γ-secretase catalytic core component, has also been found in multiple cancer cell lines, which results in the translocation of the intracellular domain (ICD) of TβR1 into the nucleus and activation of genes involved in tumor invasion." (PMID 28068334, 2017). "In combination with ADAM10 and ADAM17 inhibition decreasing GSC proliferation, these new therapeutic targets may provide a mechanism for depletion of the tumourigenic stem cell pool that seeds the tumour whilst sparing native neural stem cells." (PMID 27541285, 2017). "However, previous work have focused primarily on ADAM17 in the cancer cells and expression of ADAM17 in cells located within the tumor stroma has not been previously examined." (PMID 27738494, 2016). "Although ADAM10 mediate S2 cleavage in a ligand-dependent manner, ADAM17 cleaves Notch in the absence of ligand, a process may be important in tumours overexpressing ADAM17 protein." (PMID 27941799, 2016). "However, the contributions of ADAM17 to regulating macrophage function within the tumor microenvironment have not been examined." (PMID 27738494, 2016). "Thus we ruled out the possibility that ADAM17 promoted MC38CEA tumor growth through the activation of the growth factors for which it was identified as the main sheddase." (PMID 23251384, 2012). "Importantly, the prognostic impact of ADAM17 was independent of tumour size, grade and lymph node status." (PMID 21906355, 2011).
tumor (continued). "Although dihydrotestosterone modulates the gene expression of ADAM9, ADAM10 and ADAM17 in an androgen-dependent cell line, the expression of the ADAM species in these tumor cell lines may result mainly from the gene regulation associated with transformation of the cells." (PMID 16277668, 2005). "However, promoter methylation in other tumor types may not be the only mechanism regulating ADAM17 overexpression." (PMID 36558177, 2022). "However, there is no report yet on the regulation of ADAM17 by iRhom1 in endothelial cells and its effect on tumor malignant progression, which may be an interesting topic." (PMID 36466812, 2022). "The most recent studies on the role of ADAM17 in CRC found that the cellular level of ADAM17 may augment the malignant potential of CRC cells by increasing their motility and the expression of proangiogenic factors, which could determine tumor progression and metastasis." (PMID 31565100, 2019). "After confirming that the mock-transfection does not influence in vivo MC38CEA tumor development (data not shown) we compared the growth of tumors induced by implanting the same number (5×105) of cells of two different mock-transfected cell lines and three different ADAM17-silenced cell lines." (PMID 23251384, 2012). "In some cases, in which the exact pattern of ADAM17 expression within the tumor tissue has not been determined, it cannot be excluded that non-neoplastic cells, e.g. infiltrating macrophages, endothelial cells or stromal fibroblasts are the major source of ADAM17." (PMID 23251384, 2012). "Combining miR-126 reintroduction, which targets specific HB-EGF-active proteases but not ADAM17, with MMP inhibitors like Batimastat or Marimastat effectively suppressed tumor growth." (PMID 39419989, 2024). "These experiments revealed that ADAM17 pharmacologic inhibition reduced DLD1, but not LoVo tumor growth, as compared to control treatments." (PMID 38137406, 2023). "We subsequently examined ADAM10, ADAM17 and ADAM19 expression in the tumour cell and found that while ADAM10/17 are not induced by platelet cloaking, ADAM19 is potently induced." (PMID 30908480, 2019). "The results indicate that ADAM17 does not influence proliferation of MC38CEA cells in vitro, and suggest that ADAM17 does not promote tumor development via activation of growth factors." (PMID 23251384, 2012). "In addition, investigation of ADAM12(S&L) and ADAM17 levels in laser-capture micro dissected (LCM) samples of BC showed that all of the three genes mentioned are upregulated in benign and malignant LCM tumor and malignant non-LCM samples." (PMID 38317965, 2024). "Another possible explanation for the lack of inhibition of TNF-α shedding in vivo is that shedding in trans could be occurring, where murine ADAM17 on host cells, which would not be regulated by D1(A12), could cleave TNF-α on adjacent human tumour cells." (PMID 22792380, 2012). "Although ADAM17 is able to cleave L1 and CD44, it seems that ADAM10 and not ADAM17 is a major sheddase for these molecules and is responsible for their constitutive shedding also from tumor cells." (PMID 23251384, 2012). "When using growth factors as a stimulus, anti-ADAM10 or anti-ADAM17 significantly increased GSC migration, but this was not true for NSCs suggesting an inherent difference in cellular response to metalloproteinase inhibition between tumour and non-tumour stem cells." (PMID 27541285, 2017). "Thus, while this may not be the primary mechanism through which ADAM17 regulates Cox-2 in macrophages, it is feasible that shedding of EGF ligands into the tumor microenvironment may regulate Cox-2 expression in surrounding cell types in vivo." (PMID 27738494, 2016). "Indeed, we have established that these three inhibitors block the shedding of ADAM-17 targets such as TNFα, TGFα and amphiregulin (AREG) with the same efficacy (data not shown) whereas TMI-2 and TMI-005 only partially inhibit tumor cell growth and do not induce apoptosis." (PMID 23028451, 2012).
cancer (258 papers, 2009 to 2026). A tumor composed of atypical neoplastic, often pleomorphic cells that invade other tissues. "Dysregulation of ADAM17 activity has been implicated in various diseases, including inflammatory disorders, cancer cardiovascular and neurodegenerative diseases." (PMID 41050403, 2025). "Many of these cytokines are released by the inflammation-induced enzyme TACE/ADAM17 or associated with chronic inflammation possibly explaining the higher levels of sClever-1 in cancer patients." (PMID 40756372, 2025). "An investigation in lab-based models showed that exosome-associated ADAM17 compromises endothelial cell adhesion by cleaving VE-cadherin, thereby increasing vascular permeability and enabling cancer cell intravasation." (PMID 40427200, 2025). "Dysregulation of ADAM17 has been strongly implicated in a variety of pathological conditions including asthma, cancer, arthritis, and fibrosis." (PMID 40224489, 2025). "Absence of ADAM17 activity in mice results in developmental defects and lethality, while dysregulation of ADAM17 activity is implicated in pathologies such as chronic inflammation and cancer progression." (PMID 37119365, 2023). "Instead, we found that release of the EGFR ligands, HB-EGF and AREG, was reduced in cocultures with ADAM17-deficient cancer cells." (PMID 35998057, 2022). "Using mass spectrometry–based proteomics and ELISA, we identified heparin-binding EGF (HB-EGF) and amphiregulin, shed by ADAM17 in the cancer cells, as the implicated molecular mediators of macrophage education." (PMID 35998057, 2022). "ADAM17 and TNFα are associated with chronic inflammatory conditions predisposing to cancer formation and metastasis." (PMID 36078095, 2022). "Its ‘promiscuous’ activity and role in regulating the bioavailability of various molecules has implicated ADAM17 in cancer, neurological and inflammatory immune conditions, as well as leukocyte recruitment." (PMID 35215094, 2022). "For instance, a member of the ADAM family, ADAM17, is implicated in cancer formation and its progression." (PMID 35958270, 2022). "ADAM17 is one of the important membrane-associated metalloproteases that mediates various cellular events as well as inflammation, cancer, and other pathologies." (PMID 35906635, 2022). "ADAM17 is associated with various pathologies, including cardiovascular diseases, cancers, acute inflammatory diseases." (PMID 35354403, 2022). "The locus with segmental gains included several cancer-associated genes, e.g., Asap2 and Adam17, in the DMBA-treated organoid-derived adenocarcinomas." (PMID 34912374, 2021). "ADAM17 activity is also associated with immune evasion of cancer cells by modulating the cleavage of programmed death-ligand 1 (PD-L1)." (PMID 33579029, 2021). "The importance of the pro-domain in the regulation of ADAM17 is demonstrated in vivo by a cancer-associated point mutation that falls within its sequence (R177C)." (PMID 33579029, 2021). "ADAM17 has been found overexpressed in various human cancers including BC and has been associated with cancer progression, proliferation and migration, as well as with poor prognosis." (PMID 34070094, 2021). "We here analyzed four cancer-associated missense mutations located within the catalytic domain of the ADAM17 protein." (PMID 33143292, 2020). "In this study, we characterize ADAM17 variants found in tissue samples of cancer patients in overexpression studies." (PMID 33143292, 2020). "Utilizing an ADAM10/17 deficient HEK293 cell line, we characterized these ADAM17 variants based on their expression, cellular localization as well as their ability to cleave substrates implicated in cancer." (PMID 33143292, 2020). "In this study, we analyzed cancer-associated ADAM17 variants to gain further insight into the role of ADAM17 in disease pathways and the effect of these mutations on the protein." (PMID 33143292, 2020).
cancer (continued). "It is, however, notable that almost all cancer-associated ADAM17 mutations analyzed in this study, as well as in our previous study, seem to have a negative effect of proteolytic activity in some way." (PMID 33143292, 2020). "Among this dataset, a large percentage (34.9%) of ADAM17 mutations was found in cancer of the gastrointestinal tract." (PMID 33143292, 2020). "As both CELSR2 and ADAM17 seem to have growth‐stimulating functions, the loss‐of‐function mutations are less likely candidates for cancer predisposition." (PMID 30809968, 2019). "In this study, we screened human cancer databases to better understand the link between ADAM17 mutations and cancer progression." (PMID 31060243, 2019). "Taken together, all here analyzed cancer-associated variants of ADAM17 show unchanged or diminished proteolytic activity." (PMID 31060243, 2019). "Breaking these numbers down to individual tissues, 2331 cancer samples taken from the large intestine, which includes the caecum and colon, resulted in 40 positive samples harboring a coding mutation within ADAM17 (incidence: 1.7%)." (PMID 31060243, 2019). "Since EGF-R activation requires ADAM17 activity, it underlines the role of ADAM17 in cancer development and moreover provides a novel therapeutic target." (PMID 31060243, 2019). "In comparison to the wildtype, cancer-associated mutations of ADAM17 within the membrane-proximal- (D616N and D657A) and the cytoplasmic-domain (R725H) showed a slightly reduced, but not significantly impaired cell surface activity." (PMID 31060243, 2019). "Several ADAM family members, particularly ADAM9, ADAM10, ADAM12, ADAM15 and ADAM17, have been implicated in cancer formation and progression." (PMID 30081852, 2018). "Currently, there are over 80 substrates processed by ADAM17 and many of them are implicated in cancer and inflammatory conditions." (PMID 29230082, 2017). "ADAM17 is expressed in various tissues and has been reported to be associated with cancer progression events such as invasion, migration, and metastasis." (PMID 25177692, 2014). "For example, of the five AFAS probes designed to detect the transcripts encoded in the antisense strand of cancer-related gene ADAM metallopeptidase domain 17 (ADAM17, U69611) only U69611-04 revealed an altered expression balance with the sense transcript." (PMID 21575255, 2011). "Beyond inflammation and cancer, ADAM17 has been implicated in the pathogenesis of other diseases." (PMID 40143211, 2025). "Moreover, in primary cancers, both isoforms of ADAM17 associated remarkably with amounts of proliferating cell nuclear antigens and urokinase plasminogen activator." (PMID 38317965, 2024). "CD9 is also shown to associate directly with ADAM17 on the surface of different cell types (cis interactions), including leukocytes and cancer cells, and through this association exerts an inhibitory effect on ADAM17 sheddase activity against its substrates, including TNFα, ICAM-1 or ALCAM." (PMID 38542421, 2024). "Our work identifies that intervention at the level of iTAP/Frmd8 may be beneficial to target the inflammatory features of ADAM17 associated with iRhom2, and shows new insights of the iTAP/Frmd8-mediated sheddase complex on cancer growth regulation." (PMID 36720499, 2023). "Moreover, we found that macrophages polarized by ADAM17-deficient cancer cells showed a tendency toward decreased expression of several other protumorigenic markers." (PMID 35998057, 2022). "Confirming our BMDM data, THP-1 macrophages polarized by WT SW480 cells clearly induced the invasion of cocultured WT cancer cells, and when THP-1 macrophages were polarized by ADAM17-deficient SW480 cancer cells, the increase in cancer cell invasion was completely lost." (PMID 35998057, 2022). "In conclusion, the results of our study indicate that ADAM10 and ADAM17 may be potential biomarkers in cancer linked with DMT2 and CVD as diseases associated with inflammation." (PMID 36286024, 2022).
cancer (continued). "Interestingly, the number of disseminated macrophages was reduced when the cells were primed by ADAM17-deficient cancer cells." (PMID 35998057, 2022). "High levels of ADAM17 and soluble PD-L1 are associated with poor cancer prognosis." (PMID 33579029, 2021). "Due to the key role of ADAM17 in diverse processes and pathologies, it has been proposed as a target for developing new therapies for the treatment of inflammation and inflammation-associated cancer." (PMID 34884897, 2021). "The locus with segmental gains included several cancer-associated genes, e.g., Asap2 and Adam17." (PMID 34912374, 2021). "Otherwise, ADAM17 was associated with the prognosis of cancer patients." (PMID 32610677, 2020). "Interestingly, we found a cancer-associated point mutation within the pro-domain of ADAM17 (R177C) to be most impaired in its proteolytic activity and trafficking to the cell membrane." (PMID 31060243, 2019). "This large repertoire of substrates processed by ADAM17 places it as a pivotal orchestrator of a myriad of physiological and pathological processes associated with the initiation and/or progression of cancer, such as cell proliferation, survival, regeneration, differentiation and inflammation." (PMID 31438559, 2019). "Notably, ADAM10 and ADAM17 mutations are associated with many diseases in humans, including a variety of cancers." (PMID 28068334, 2017). "Additionally, elevated EGFR signalling caused by excess ADAM17 activity is associated with cancer progression." (PMID 27731361, 2016). "However, there is evidence suggesting an association between increased expression of ADAM17 and various types of cancer." (PMID 27803674, 2016). "Thus, ADAM17 is implicated in different human diseases, including cancer, and is a promising target for treatment." (PMID 27381289, 2016). "Overexpression of ADAM17, accompanied by an increased shedding of numerous growth factors, cytokines, and cell adhesion molecules, has been widely linked to the progression of cancer and the promotion of inflammation." (PMID 26176220, 2015). "These events dictated by ADAM17 were previously associated with other cancer cell lines." (PMID 24495306, 2014). "ADAM17 expression is elevated in different cancers and is associated with cancer progression." (PMID 23076445, 2013). "Interestingly, CD, m62A, and TQ dose-dependently reduced ADAM17 protein levels in different cancer cells, but mRNA levels were not reduced, implying the potential of the three compounds in improving viral susceptibility in patients with malignant tumors." (PMID 36558177, 2022). "However, the precise molecular mechanism underlying the role of cancer cell-derived exosomal ADAM17 in metastasis remains unclear." (PMID 34650435, 2021). "Since the catalytic domain of ADAM17 is the only region structurally determined by crystallography, we study the effect of each point mutation not only to learn more about the role of ADAM17 in cancer, but also to investigate the structure–function relationships of the metalloprotease." (PMID 33143292, 2020). "Similarly, the formation of 3‐dimensional spheroid aggregates was dramatically diminished in A549 cells either deficient in ADAM17 or treated with A17pro, suggesting that ADAM17 can also impact on the proliferative capacity of cancer stem (i.e., initiating) cells in LAC (Figs EV5G and 5H)." (PMID 30833304, 2019). "A novel feature of TAB16 is its dual functionality, as it synergizes with IL-15 to enhance NK cell activation and proliferation and targets ADAM17 overexpressed on cancer cells to induce ADCC." (PMID 41694365, 2026). "A300E, which is rapidly internalized and exhibits an IC50 of approximately 0.7 mg/mL against ADAM17, facilitates the targeted delivery of conjugated toxins into cancer cells." (PMID 41050403, 2025). "Dysregulation of ADAM-17 contributes to inflammatory diseases, cancer progression, and immune modulation." (PMID 41594573, 2025).